GPR42 (G protein-coupled receptor 42)
Description:
G protein-coupled receptor that is activated by short chain fatty acids (SCFAs), such as propionate. Hence may play a role in the regulation of whole-body energy homeostasis and/or in intestinal immunity.
Synonyms: GPR42P; GPR41L; FFAR3L; FFAR1L
Tractability: Small molecule: it belongs to a druggable protein family. Antibody: its Gene Ontology location is reachable by antibodies, with high confidence; UniProt places it where antibodies can reach, with medium confidence; UniProt predicts a signal peptide or a membrane-spanning region.
Gene: Protein-coding gene on chromosome 19 (35,371,068 to 35,372,962, forward strand). Ensembl gene ENSG00000126251.
Subcellular location: Cell membrane
Gene Ontology:
Molecular function: G protein-coupled receptor activity; protein binding
Biological process: G protein-coupled receptor signaling pathway
Cellular component: plasma membrane; membrane
Genetic constraint (gnomAD): Loss-of-function variants: 0 observed, 0.23 expected, observed/expected ratio (o/e) 0, 90% interval 0 to 1.87. That is too few expected variants to judge how well the gene tolerates losing a copy. Missense variants: 10 observed, 12.7 expected, observed/expected ratio (o/e) 0.79, 90% interval 0.49 to 1.34. Synonymous variants: 7 observed, 5.4 expected, observed/expected ratio (o/e) 1.3, 90% interval 0.71 to 1.9.
Homologues: Orthologues: chimpanzee FFAR3 (98% identical), mouse Ffar3 (69% identical), rat Ffar3 (68% identical), zebrafish si:ch73-90p23.1 (38% identical), zebrafish si:dkey-211g8.6 (37% identical), zebrafish si:dkey-211g8.7 (33% identical). Paralogues in human: FFAR3 (98% identical), FFAR2 (37% identical), FFAR1 (27% identical), P2RY1 (22% identical), P2RY2 (22% identical), HCAR3 (21% identical), HCAR2 (21% identical), P2RY6 (21% identical), P2RY4 (20% identical), GPR31 (20% identical), SUCNR1 (20% identical), OXGR1 (19% identical), and 3 more.